CT47A9 (cancer/testis antigen family 47 member A9)
Synonyms: CT47.9
Gene: Protein-coding gene on chromosome X (120,943,561 to 120,946,883, reverse strand). Ensembl gene ENSG00000226600.
Subcellular location (Human Protein Atlas): Nucleoli
Homologues: Orthologues: macaque CT47B1 (77% identical). Paralogues in human: CT47A1 (100% identical), CT47A10 (100% identical), CT47A11 (100% identical), CT47A12 (100% identical), CT47A2 (100% identical), CT47A3 (100% identical), CT47A4 (100% identical), CT47A5 (100% identical), CT47A6 (100% identical), CT47A7 (100% identical), CT47A8 (100% identical), CT47B1 (86% identical), and 1 more.